HOTAIR (HOX transcript antisense RNA)
Diseases named in the same sentence as HOTAIR in open-access papers (continued):
Sharing a sentence is not in itself a finding about the gene and the disease.
tumor (continued). "Another study revealed that HOTAIR functions as a “miRNA sponge” that silenced miRNAs (tumor suppressor), and thereby induced the overexpression of oncogenic genes." (PMID 32117729, 2020). "HOTAIR is a prognostic factor for various kinds of tumors, but the understanding of its role in tumor pathogenesis remains limited." (PMID 32394637, 2020). "In GBM, HOTAIR was involved in the invasion, proliferation, colony formation, cell cycle, tumour growth in mice and the overall survival of GBM patients." (PMID 32279420, 2020). "The oncogenic and tumor suppressor actions of HOTAIR and GAS5, respectively, have been also described for other lncRNAs." (PMID 32967233, 2020). "HOTAIR expression levels are significantly high inbreast tumours, and its measurement is a determinativeindicator of primary breast tumours, possibility ofmetastasis and patient survival." (PMID 31721532, 2020). "The expression of HOTAIR in patients' saliva was significantly reduced after the PDAC tumor was surgically removed." (PMID 32257946, 2020). "Estradiol promotes HOTAIR through its GPER receptor by inhibiting miR-148a, and estrogen-induced migration of tumor cells is reversed by eliminating HOTAIR in TNBC cells." (PMID 33171872, 2020). "We also identified HOTAIR functions as a ceRNA modulate the tumor microenvironment by control the level exosomal miRNAs." (PMID 32951010, 2020). "Our data revealed HOTAIR is overexpressed in primary GBM tumour, particularly in recurrent GBM patients." (PMID 32279420, 2020). "In BRCA, lncRNAs are emerging as master regulators in tumor biology, and have oncogenic and tumor suppressor functions related to initiation and cancer progression, some examples are HOTAIR, MALAT-1, lincRNAp21, and GAS5." (PMID 32753692, 2020). "As reviewed above, HOTAIR upregulates the expression of HLA-G in tumor tissues, which indicated the potential role of HOTAIR as a biomarker of tumor immune escape." (PMID 32083005, 2020). "HOTAIR is an intergenic lncRNA that functions as an oncogene by promoting tumor cell growth, invasion, metastasis and drug resistance." (PMID 33291485, 2020). "Further investigations have highlighted the correlation between higher expression of HOTAIR and enhanced proliferation and migration ability of CSCC cells in vitro, and an increased tumor growth in vivo, otherwise attenuated by the HOTAIR silencing." (PMID 32911687, 2020). "In TME, HOTAIR is able to modulate different molecular pathways involved in tumor phenotype modifications during metastatic progression." (PMID 32397382, 2020). "In these cells, HOTAIR promotes the transition of tumor cells from G1 phase to S phase and inhibits the apoptosis." (PMID 32397382, 2020). "The TGCA database analysis indicated that HOTAIR expression was also higher in GBM primary tumours and led to reduced survival of GBM patients." (PMID 32279420, 2020). "The results of the current study displayed that silencing of HOTAIR promoted chemosensitivity to 5-FU and apoptosis while repressing cell proliferation and tumor growth in EC." (PMID 32653028, 2020). "In summary, these findings indicate that HOTAIR promotes xenografted PCa tumor growth by activating STAT3 signaling and increasing PCSLCs population." (PMID 32657763, 2020). "Many studies have highlighted the role of HOTAIR also in tumor microenvironment (TME) intracellular signaling." (PMID 32397382, 2020). "TGF-β stimulation encourages cancer cells to express more HOTAIR, which is a well-known epigenetic silencer that promotes tumor progression and metastasis." (PMID 33050576, 2020). "In liver cancer, HOTAIR is overexpressed and strongly correlates with clinical-pathological features, and tumor progression." (PMID 32397382, 2020). "In this review, we will discuss the role of the lncRNA HOTAIR in BC, highlighting in particular its contribution to tumor progression and drug resistance mechanisms and suggesting its potential use as therapeutic target." (PMID 32397382, 2020).
tumor (continued). "The HOTAIR rs7958904 CC genotype was highly expressed in tumor tissue than normal tissues (P < 0.01)." (PMID 32117729, 2020). "The upregulation of HOTAIR (Hox lncRNA) has been shown to increase tumor growth, as well as chemoresistance through the Wnt/β-catenin pathway in colon cancer." (PMID 32575858, 2020). "Consistent with the subcutaneous tumour model, depletion of HOTAIR reduced the tumour volume in intracranial tumours and extended the survival of mice." (PMID 32279420, 2020). "The tumor microenvironment (TME) plays an important role during tumor growth and metastatic progression, and HOTAIR has been found function as a key regulator of the TME." (PMID 32951010, 2020). "In NSCLC tumor tissues and A459 cell line, HOTAIR would also upregulate CSC-related biomarkers such as NANOG, POU5F1, SOX2, MYC, CTNNB1, and KLF4." (PMID 32438606, 2020). "Other co-workers have also confirmed that depletion of lncRNA HOTAIR contributes to the inhibition of cell proliferation and tumor metastasis and facilitation of apoptosis in ESCC, corresponding with the findings of the present study." (PMID 32653028, 2020). "NPC patients with high tumor HOTAIR expression levels had a worse OS prognosis than patients with low HOTAIR expression." (PMID 32117729, 2020). "HOTAIR enhances the malignant behavior of tumors mainly by remodeling the chromatin state of promoter genes, and by sponging microRNAs with tumor suppressor functions leading to tumor progression." (PMID 32466537, 2020). "The Western blot of tumour tissues revealed the HOTAIR knockdown suppressed the expression of HK2 and Ki‐67, a marker of proliferation." (PMID 32279420, 2020). "Mouse xenograft tumor models were established to investigate the influence of HOTAIR knockdown on CRC radioresistance in vivo." (PMID 32144238, 2020). "In both sets, expression of CASC9 and HOTAIR was low in most normal tissues and often undetectable, but was strongly increased in most tumor samples." (PMID 31412811, 2019). "A last, in vivo assay was performed to assess the tumor formation in nude mice in order to explore the roles of HOTAIR and HOXA5 in cell apoptosis and proliferation." (PMID 31168296, 2019). "HOTAIR promotes tumor progression through the interactions with multiple downstream signaling pathways, such as tumor suppressor PTEN." (PMID 31171714, 2019). "Further analyses of clinical datasets revealed correlations of the expression of HOTAIR with tumor metastasis and a poor survival rate in patients with UCC." (PMID 30813594, 2019). "CCL2 is required for TAM and MDSCs recruitment in the tumor microenvironment, suggesting that HOTAIR has a main role in the modulation of this process promoting tumor growth and metastasis." (PMID 31072041, 2019). "The results also showed that there is a great difference of HOTAIR expression between groups with different tumor differentiation, lymph node, and distant metastasis." (PMID 31281803, 2019). "It is also a hub lncRNA that binds mRNAs and lncRNAs, including HOTAIR, and is an epigenetically regulated tumor suppressor that is essential for activation of the DNA damage response." (PMID 31890219, 2019). "It was worth noting that the expression level of HOTAIR in saliva of OSCC metastatic patient was different from that of primary tumor controls." (PMID 31133028, 2019). "HOTAIR has been verified to be involved in the occurrence mechanisms of cervical cancer and breast cancer by promoting tumor cell migration and proliferation." (PMID 31649487, 2019). "On the other hand, HOTAIR knockdown reduces tumor invasion and increases cell apoptosis in vitro and inhibits LSCC xenograft growth in vivo." (PMID 31336999, 2019). "In contrast, the number and volume of metastatic nodules in the lung of mice injected with ADQ were significantly reduced as compared with that injected with MDA-MB-231-control cells, indicating that ADQ efficiently represses HOTAIR-mediated tumor metastasis." (PMID 30764859, 2019).
tumor (continued). "Several lncRNAs are described as able to directly or indirectly modulate neo-angiogenesis in TME, but between these, HOTAIR appears to have a fundamental role in the promotion of angiogenesis during tumor progression." (PMID 31072041, 2019). "Our findings highlight the anti-tumor ability of HOTAIR silencing in AML, suggesting that silencing HOTAIR was able to inhibit AML progression through HOXA5 promoter demethylation by decreasing Dnmt3b." (PMID 31168296, 2019). "OPN is able to induce HOTAIR expression in a dose and time-dependent manner in different tumor cell lines, while OPN knockdown decreases HOTAIR expression." (PMID 31072041, 2019). "In fact, HOTAIR knockdown significantly inhibited both in vitro and in vivo tumor cell growth and angiogenesis." (PMID 31336999, 2019). "It was shown that CCL2 is a downstream target of HOTAIR and is involved in the recruitment of myeloid-derived suppressor cells (MDSCs) and macrophages to the tumor microenvironment." (PMID 31056726, 2019). "HOTAIR promotes tumor progression by acting as a micro (mi)RNA sponge and promoting an immunosuppressive tumor microenvironment." (PMID 31477638, 2019). "While HOTAIR expression is induced upon hypoxia, several HOTAIR target genes and tumor suppressors such as HOXD10, HOXD8, PCDHGA8, and PCDHB5 are down-regulated under hypoxic conditions." (PMID 31072041, 2019). "They found that Jagged 1 and Notch 1 expression decreased after HOTAIR knockdown, indicating that HOTAIR regulates tumor progression in Rb through the activation of the Notch 1 pathway." (PMID 31798638, 2019). "HOTAIR has been demonstrated to promote tumor cell invasion and metastasis by modulating epithelial-to-mesenchymal transition (EMT)." (PMID 31195674, 2019). "In LSCC tissues HOTAIR expression, is 16-fold higher compared to normal tissues, and this increase is correlated with advanced tumor grade, lymph node metastasis, poor differentiation and advanced clinical stages." (PMID 31336999, 2019). "In renal cell carcinoma (Rcc) HOTAIR is able to promote tumor progression through inhibition of miR-217 expression, and modulating the expression of HIF-1α and AXL receptor tyrosine kinase." (PMID 31072041, 2019). "HOTAIR is required for tumor metastasis because of its key function in different signaling mechanisms related to EMT." (PMID 30617305, 2019). "Our research demonstrated the role of HOTAIR in exosome secretion and provides a new understanding of lncRNAs in tumor cell biology." (PMID 30943982, 2019). "Previous study showed that HOTAIR promotes the invasion and metastasis of tumor cells and inhibits the apoptosis of tumor cells." (PMID 31882666, 2019). "The results displayed that down-regulation of HOTAIR decreased the tumor volume and tumor weight after the 4-week intratumorally injection." (PMID 31649487, 2019). "Among 31 patients’ tumor tissue samples tested, about 19 (61.2%) patients showed high expression of both HOTAIR and MKL1." (PMID 29391067, 2018). "Mutations in lncRNAs like HOTAIR, MALAT1, ANRIL, h19 and PCA3 have been reported in a number of tumor types." (PMID 29732012, 2018). "Emerging evidence indicated that in the process of tumor progression, lncRNA HOTAIR plays an imperative role." (PMID 30111807, 2018). "Compared to DCIS, HOTAIR expression and nuclear staining were higher in metastatic breast carcinoma, as revealed by FISH images, which indicated that the upregulation of HOTAIR strongly correlated with tumor metastasis." (PMID 29325547, 2018). "Specifically, mounting evidence has revealed that the up-regulation of HOTAIR contributed to drug resistance and tumor metastasis in various types of solid tumors." (PMID 29325547, 2018). "Meanwhile, knockdown of HOTAIR in C4-2B cell line dramatically suppressed cell proliferation and cell invasion, indicating HOTAIR was tumor-progression driver in CRPC and increased PC cell growth and invasion." (PMID 30037351, 2018).
tumor (continued). "The tumor volume was measured and the expression of HOTAIR in tumors was detected by quantitative real-time PCR." (PMID 30355300, 2018). "Conversely, loss of HOTAIR expression in urothelial bladder cancer cell lines inhibits epithelial-to-mesenchymal transition (EMT), which is responsible for tumor metastasis." (PMID 29678180, 2018). "Effect of HOTAIR overexpression on tumor growth in mice bearing C33A cells and exposed to radiation." (PMID 30355300, 2018). "Highly expressed HOTAIR is correlated with tumor size and lymph node metastasis, while H19 can contribute to higher patient relapse." (PMID 29416703, 2018). "PRC2 plays a significant role in tumour progression through binding of HOTAIR (a very well-studied lncRNA)." (PMID 29757368, 2018). "Treatment with a BET inhibitor (I-BET151) decreases expression of HOTAIR and suppresses tumor cell proliferation by inducing cell cycle arrest." (PMID 28187439, 2017). "Second, HOTAIR expression level was significantly decreased in xenograft tumor tissues which were generated from PC3 cells stably overexpressing miR-193a (P < 0.05)." (PMID 29141691, 2017). "To determine why HOTAIR is crucial for tumor cell survival, we performed a miRNA microarray assay to screen for miRNAs regulated by HOTAIR." (PMID 28182000, 2017). "The expression of HOTAIR was compared between the tumor (n = 1,066) and normal samples (n = 133) of TCGA tissues." (PMID 29209357, 2017). "The expression level of HOTAIR was correlated with tumor size and clinical stage in OSCC and HOTAIR has been suggested as a prognosis factor for HNSCC." (PMID 29228709, 2017). "Although the involvement of HOTAIR in tumor-igenesis has been reported extensively, its role in the development and progression of RCC and the underlying mechanisms have not been clearly demonstrated." (PMID 28938586, 2017). "Other well-characterized lncRNAs contain HOTAIR, ANRIL and H19, whose expression level also increased in NSCLC, whereas GAS5 and MEG3 are associated with tumor-suppressive function." (PMID 28415568, 2017). "A second study published in the same year reported upregulation of HOTAIR in surgically resected tumor tissue from 63 HCC patients compared with adjacent non-tumor tissues." (PMID 30159431, 2017). "Amount of each HOTAIR isoform in each tumor tissue was determined using transcript per million reads (TPM)." (PMID 28846832, 2017). "For example, overexpression of HOTAIR and MALAT-1 were found to be associated with tumor recurrence of HCC after liver transplantation." (PMID 28729955, 2017). "HOTAIR knockdown significantly inhibited tumor growth, whereas HOTAIR overexpression promoted tumor growth." (PMID 28938586, 2017). "By studying murine xenograft models, researchers found that HOTAIR knockout can reduce the growth of tumor in vivo." (PMID 29299179, 2017). "HOTAIR (HOX antisense intergenic RNA) is one of the most intensively studied lncRNAs, as it is frequently associated with different neoplasias." (PMID 29147648, 2017). "In summary, the upregulation of HOTAIR frequently occurs in gynecologic malignancies and usually predicts tumor metastases and poor prognosis." (PMID 28649178, 2017). "The results showed that high HOTAIR expression was significantly correlated with advanced clinical tumor stage, lymph node metastasis, poor differentiation, and large tumor size." (PMID 28591050, 2017). "In CD117+CD44+ CSCs, tumor growth and metastasis were significantly inhibited by downregulation HOTAIR expression." (PMID 29110645, 2017). "Studies of HOTAIR in other malignancies have mainly focused on its effects on tumor invasion/migration and the eventual development of metastases; however, HOTAIR can strongly enhance cell proliferation by accelerating cell cycle progression." (PMID 28649178, 2017). "It revealed that the origin of HOTAIR derived from tumor cells and serum HOTAIR was down-regulated after the tumor resection." (PMID 28376832, 2017).
tumor (continued). "To validate the aberrant expression of HOTAIR in clinical specimens, we collected samples of non-tumor (N), local tumor (T) and lymph node (LN) tissues from OSCC patients and these samples were subjected to real-time RT-PCR analysis." (PMID 29228709, 2017). "The study also confirmed that HOTAIR inhibition, through short hairpin RNA antagonist employment in murine tumour xenograft models for small cell lung cancer, led to a reduction in tumour growth." (PMID 28273813, 2017). "The expression of HOTAIR was elevated in the tumor samples compared with non-tumor tissues from the same patients." (PMID 29228709, 2017). "It was first reported that lncRNA HOTAIR silences the tumor suppressor genes by interacting with EZH2 and enhancing H3K27me3." (PMID 28854977, 2017). "The results revealed that high expression of HOTAIR was related to larger tumor size ( > 4 cm vs ≤ 4 cm: OR = 2.19, 95%CI 1.42-3.38, P = 0.000)." (PMID 29108287, 2017). "The significant correlation between HOTAIR expression and tumor size was identified by qRT-PCR (OR = 1.40, 95% CI = 1.03–1.91, P = .03), but not by ISH." (PMID 28591050, 2017). "Additional studies aimed at understanding the molecular mechanisms by which HOTAIR impacts tumor cell development have been recently undertaken." (PMID 30159431, 2017). "HOTAIR promotes tumor invasion and metastasis by silencing tumor suppressors, and activating oncogenes and signaling pathways." (PMID 28649178, 2017). "When deregulated, HOTAIR recruits PRC2 subunits in promoter regions of tumor suppressor genes which results in their transcriptional repression and chromatin condensation, thus, favoring tumor progression." (PMID 28634418, 2017). "Recent studies have reported that the level of HOTAIR expression is distinctly upregulated in tumor tissues, including breast cancer, liver cancer, ovarian cancer, gastric cancer, and NSCLC." (PMID 28415568, 2017). "It is interesting to note that both HOTAIR and MEG3 bind GA-rich sequence elements that facilitate recruitment of PRC2 complex and condense the local chromatin environment, yet HOTAIR functions as an oncogene while MEG3 functions as a tumor suppressor." (PMID 29113413, 2017). "Depletion of HOTAIR in enzalutamide-resistant PCa cells results in the recovery of their sensitivity to enzalutamide and decreased tumor growth." (PMID 28938586, 2017). "In the current study, we examined the significance of lncRNA HOTAIR (HOX transcript antisense RNA) in tumor progression of oral squamous cell carcinomas (OSCC)." (PMID 29228709, 2017). "We found the expression of HOTAIR was upregulated in tumor tissues, especially in the metastatic samples." (PMID 29228709, 2017). "It means that HOTAIR is involved in tumor metastasis of RCC partly through increasing the JMJD3-mediated SNAI1 upregulation." (PMID 28177890, 2017). "HOTAIR (HOX transcript antisense RNA, HOTAIR), a 2337nt lncRNA located at 12q13.13, has a high expression in OS tumor tissues, and notably promotes tumor growth." (PMID 28103585, 2017). "The serum levels of HOTAIR were correlated with tumor size, tumor-node-metastasis (TNM) stage and lymph node metastasis (P < 0.05), but not with age, gender, smoking, differentiation and histology (P > 0.05)." (PMID 28641698, 2017). "Several well-characterized lncRNAs, such as HOTAIR, FAL1, NKILA, LSINCT5, and BCAR4, exhibit aberrant expression in cancer tissues and are associated with tumor progression and/or metastasis." (PMID 28558830, 2017). "HOTAIR is posttranscriptionally destabilized by several tumor suppressor miRNAs in different cancers." (PMID 29147648, 2017). "Among the 6 studies that reported lncRNAs function as tumor oncogenes and used tumor weight as the major outcome measure, 5 different lncRNAs (HOTAIR, TUG1, BCAR4, MALAT1 and FGFR3-AS1) were reported." (PMID 29245999, 2017).